BBS2 (Bardet-Biedl syndrome 2)
Diseases named in the same sentence as BBS2 in open-access papers:
BBS2 is named in the same sentence as 88 diseases in open-access papers, as found by Europe PMC text mining. Sharing a sentence is not in itself a finding about the gene and the disease. The quoted sentences say what the papers report.
Bardet-Biedl syndrome (48 papers, 2006 to 2025). A ciliopathy with multisystem involvement. "Variants in the BBS2 gene are closely associated with severe visual impairment in patients with Bardet-Biedl syndrome (BBS)." (PMID 41259386, 2025). "A homozygous missense variant in the BBS2 gene (chr16:56,548,501 C > T, p.S70N), which is one of the Bardet Biedl syndrome (BBS) gene family, was also identified." (PMID 38919843, 2024). "BBS2 is a basal body-associated protein necessary for proper ciliogenesis, and mutations in BBS2 lead to RP and a ciliopathy called Bardet-Biedl syndrome." (PMID 33435268, 2021). "These include the BBSome complex, a stable heptameric structure consisting of eight subunits, namely, the Bardet Biedl Syndrome (BBS)-associated proteins and interacting proteins (BBS1, BBS2, BBS4, BBS5, BBS7, BBS8, BBS9 and BBIP10/BBS18/BBIP1)." (PMID 34356089, 2021). "An interesting case is also represented by patient RP_38, who presented disease mutations in a gene causative of Usher Syndrome (USH2A), Bardet-Biedl Syndrome (BBS2), retinitisp (AIPL1) and choroideremia (CHM)." (PMID 33374679, 2020). "Another situation is encountered in genetically heterogeneous diseases with founder mutations in different underlying genes as is the case with Bardet-Biedl syndrome where two founder mutations affecting both BBS2 and BBS8 genes were reported." (PMID 22908982, 2012). "We examined the genes IFT57 (mutated in orofaciodigital syndrome (OFD, OMIM #311200)), BBS2 (Bardet-Biedl syndrome (BBS, OMIM #209900)), (TMEM231 (Meckel-Gruber syndrome (MKS, OMIM #249000)), TCTN2 (Joubert syndrome, (JBTS, OMIM #213300))." (PMID 32445086, 2020). "BBS2 is a ciliary protein involved in the pathogenesis of Bardet-Biedl syndrome (BBS), a genetically heterogeneous disease characterized by obesity, diabetes, and hyperphagia." (PMID 40231468, 2025). "Patient 3 had Bardet–Biedl syndrome and carried a heterozygous mutation (c.389_390delAC; p.Asn130ThrfsTer4) in BBS7 and a homozygous mutation in BBS2 (c.209G>A; p.Ser70Asn)." (PMID 36672825, 2022). "Proband 28 had a compound heterozygous BBS2 (OMIM * 606151) variant and was diagnosed with Bardet–Biedl syndrome; he exhibited fourth toe brachydactyly in both feet, which was more severe in the right foot." (PMID 31960602, 2020). "Patient RP_37 showed causative homozygous variants in genes related to Usher Syndrome (MYO7A) and Bardet-Biedl Syndrome (BBS2)." (PMID 33374679, 2020). "Regarding BBS2, it is a member of the Bardet-Biedl syndrome (BBS) gene family." (PMID 32116524, 2020). "Of the genes affecting cilia function, two are orthologs of the Bardet-Biedl syndrome (BBS) family of genes (bbs-1 and bbs-2)." (PMID 39773880, 2025). "Among these cases, 10 had Bardet-Biedl syndrome (BBS), comprising eight BBS2 patients and two BBS7 patients." (PMID 38671463, 2024). "Moreover, carrier frequencies based on GnomAD do not necessarily correspond to the epidemiology of the disorders: BBS2 for example has a higher carrier frequency than BBS1 in GnomAD, while the latter is much more commonly mutated in patients with the corresponding ciliopathy Bardet-Biedl syndrome." (PMID 36550190, 2023). "However, in BBS No.10, three variants were found, two of which in BBS2 and BBS8 genes were classified as VUS (variant of uncertain significance) and one variant in BBS10 gene was described as likely benign, but potentially causative for Bardet–Biedl syndrome." (PMID 33138063, 2020).
Obesity (39 papers, 2009 to 2025). Accumulation of substantial excess body fat. "A 31-year-old female with BBS, with homozygous pathogenic variant in the BBS2 gene, presented with obesity, dyslipidemia, and obstructive sleep apnea." (PMID 40741596, 2025). "Conversely, our investigation did not reveal any significant links between individuals carrying rs773862084 variants in BBS2 and overweight or obesity." (PMID 38617006, 2024). "Disruption of BBS2 is specifically associated with adult obesity whereas BBS4 and BBS6 have been linked to both adult and childhood obesity." (PMID 37064917, 2023). "In mice, loss of Bbs2, Bbs4 and Bbs6 causes hyperphagia, obesity and hyperleptinemia, and hypothalamic neurons of Bbs4−/− mice lack ciliary localization of appetite-regulating G-protein coupled receptors." (PMID 27482817, 2016). "Inactivation of Bbs2, Bbs4 and Bbs6 genes leads to obesity associated with increased food intake and with hyperleptinemia and leptin resistance." (PMID 19439065, 2009). "Due to limited clinical information, there is insufficient evidence to support the hypothesis of an association between the BBS2 c.1222G>C variant and an increased appetite or obesity." (PMID 34828377, 2021). "Common adult obesity was associated with nucleotide polymorphism in BBS2 (rs4784675)." (PMID 34573333, 2021). "The identification of BBS2 mutations reaffirms the importance of ciliary pathways in the pathogenesis of BBS, leading to characteristic features such as retinal dystrophy, obesity, polydactyly, and renal anomalies." (PMID 38919843, 2024). "Patients with BBS2 mutations have a higher incidence of polydactyly, and BBS10 gene mutations are linked to more pronounced obesity and insulin resistance." (PMID 39126056, 2024). "At around 4 months, Bbs1M390R knock-in, Bbs2 −/−, Bbs4 −/−, Bbs6 −/−, and Bbs7 −/− mice developed obesity characterized by hyperphagia." (PMID 37064917, 2023). "Bbs2, Bbs4, Bbs6, and Bbs12 KOs, as well as a Bbs1M390R/M390R knock-in animals, develop obesity driven by hyperphagia." (PMID 35653384, 2022). "Germline ablation of the Bbs2 and Bbs4 (Bbs2−/− and Bbs4−/−) genes led to hyperphagia-induced obesity, coupled with reduced phosphor-STAT3 levels in the hypothalamus." (PMID 34211092, 2021). "We previously determined that obesity in BBS mutant mice (Bbs1M390R, Bbs2-/-, Bbs4-/- and Bbs6-/-) was associated with hyperphagia and leptin resistance." (PMID 26926121, 2016). "However, our findings are consistent with previous studies of other BBSome genetic knockouts (Bbs2–/– and Bbs4–/–), which demonstrate that dysregulated leptin receptor signaling is a key ciliopathy-mediated disruption contributing to obesity in BBS." (PMID 40233116, 2025). "Furthermore, Bbs2-, Bbs4-, and Bbs6-null mice exhibit high circulating leptin levels at an early age and before the development of obesity." (PMID 37571382, 2023). "Further analysis of BBS resulted in development of BBS knockout mice (Bbs2, Bbs4 and Bbs6) that developed hyperphagia, reduced energy expenditure and increased circulating leptin levels, which suggests that leptin deficiency is not the mechanism of obesity in BBS." (PMID 25825681, 2015). "Other studies have shown that Bbs2-, Bbs4-, and Bbs6-knockout mice are leptin resistant, independent of obesity; and in these models, hypothalamic leptin receptor signaling was impaired." (PMID 40519161, 2025). "Strikingly, the fasting insulin levels of calorie restricted Bbs2-/-, Bbs4-/-, and Bbs6-/- mice are significantly elevated indicating that the hyperinsulinemia associated with BBS is independent of obesity." (PMID 26103456, 2015).
ciliopathies (28 papers, 2006 to 2025). "Mutations in BBS2 account for 8% of BBS cases and are also implicated in other ciliopathies, such as Meckel syndrome." (PMID 39773880, 2025). "Our strategy, based on first applying several filters to ciliary variants and using many of the bioinformatics tools available, allowed us to identify causal mutations in BBS2, ALMS1 and CRB1 genes in four families, thus confirming the molecular diagnosis of ciliopathy." (PMID 28800606, 2017). "Bardet–Biedl syndrome (BBS) was classified as a ciliopathy in 2003, and eight of the highly conserved BBS proteins (BBS1, BBS2, BBS4, BBS5, BBS7, BBS8, BBS9, and BBIP10) establish a stable protein complex called the BBSome that undergoes IFT." (PMID 37208194, 2023). "The recovery of full-length BBS2 and ALMS1 expression and correction of anatomical and functional ciliary defects suggests TRIDs are a potential therapeutic option for the treatment of nonsense-mediated ciliopathies." (PMID 34365092, 2021). "The recovery of full-length BBS2 and ALMS1 expression and correction of anatomical and functional ciliary defects in BBS2Y24*/R275* and ALMS1S1645*/S1645* fibroblasts suggest TRIDs are a potential therapeutic option for the treatment of nonsense-mediated ciliopathies." (PMID 34365092, 2021).
retinal degeneration (12 papers, 2013 to 2024). Degeneration of the retina. "In addition to pleiotropic disorder, there are also reports of non-syndromic retinal degeneration caused by mutations in the BBS genes BBS1, BBS2, ARL6/BBS3, and TTC8, disrupting the normal function of photoreceptor cilia." (PMID 32962042, 2020). "Previous work had demonstrated that both cep290 and bbs2 mutants undergo slow retinal degeneration with increased retinal inflammation." (PMID 37293546, 2023). "Although both cep290 and bbs2 mutants undergo proliferation of rod precursors in response to retinal degeneration, the process of negatively regulating proliferation is enriched for upregulated genes, and this negative regulation may restrict proliferation of Müller glia and inhibit regeneration." (PMID 37293546, 2023). "Mutations in BBS2, a component of the BBSome, result in BBS as well as non-syndromic retinal degeneration in humans and rod degeneration in mice, but the role of BBS2 in cone photoreceptor survival is not clear." (PMID 33324636, 2020).
Insulin resistance (5 papers, 2015 to 2025). Increased resistance towards insulin, that is, diminished effectiveness of insulin in reducing blood glucose levels. "Genetic knockout of BBS2 in mice results in hepatic insulin resistance." (PMID 40231468, 2025).
Nystagmus (3 papers, 2017 to 2024). Rhythmic, involuntary oscillations of one or both eyes related to abnormality in fixation, conjugate gaze, or vestibular mechanisms. "The two patients with biallelic mutations in BBS2 had a BCVA ≤ 0.02 decimal and nystagmus; one of them also developed exotropia in the second decade of life." (PMID 28143435, 2017).
retinitis pigmentosa (3 papers, 2021 to 2023). Retinitis pigmentosa (RP) is an inherited retinal dystrophy leading to progressive loss of the photoreceptors and retinal pigment epithelium and resulting in blindness usually after several decades. "In addition to renal dysplasia, BBS2 mutations often cause retinitis pigmentosa, a progressive retinal degenerative disease that cannot be observed in the prenatal period." (PMID 37880672, 2023).
Rod-cone dystrophy (3 papers, 2021 to 2024). An inherited retinal disease subtype in which the rod photoreceptors appear to be more severely affected than the cone photoreceptors. "An excellent example is Bardet-Biedl Syndrome 2 (BBS2) which is a heritable cause of an autosomal recessive syndrome characterized by central obesity, rod-cone dystrophy, renal and vascular abnormalities that emanate from a central defect in cilia assembly and synaptic function." (PMID 34479557, 2021). "A total of 16 patients (26%) were found to have a cone or cone-rod dystrophy, but it appears to be distributed evenly between BBS subtypes (3/15 BBS1, 2/3 BBS2, 3/3 BBS3, 1/5 BBS9, 5/20 BBS10, and 2/3 BBS12)." (PMID 35886001, 2022).
chronic kidney disease (2 papers, 2024 to 2025). Impairment of the renal function secondary to chronic kidney damage persisting for three or more months. "However, regardless of their body mass index (BMI), individuals possessing the CA/AA genotype for BBS2 rs773862084 or the CT/TT genotype for MKS1 rs199910690 did not exhibit an increased risk of developing chronic kidney disease (CKD)." (PMID 38617006, 2024).
Hearing impairment (2 papers, 2023 to 2024). A decreased magnitude of the sensory perception of sound. "BBS2 had higher hearing impairment and lower renal abnormality penetrance." (PMID 38034494, 2023).
McKusick-Kaufman syndrome (2 papers, 2015 to 2017). McKusick-Kaufman syndrome is a very rare, genetic developmental disorder presenting in the neonatal period characterized by genitourinary malformations, polydactyly, and more rarely, congenital heart disease or gastrointestinal malformations. "BBS2 and BBS4 mutations cause BBS, whereas BBS6 (or MKKS) gene defects are associated with McKusick-Kaufman syndrome (abnormalities in finger, heart and genitals) in addition to BBS." (PMID 25650393, 2015).
retinal diseases (2 papers, 2019 to 2025). "Additionally, a study exploring the genetic landscape of retinal diseases in northwestern Pakistan identified prevalent mutations in genes such as ABCA4, BBS2 and CNGA1 as the most frequently associated IRD genes." (PMID 40141357, 2025).
Anosmia (1 paper, 2025). An inability to perceive odors. "Loss of function in the BBS2, BBS4, or BBS8 genes and their requisite proteins has been identified in dogs with progressive retinal atrophy, concurrent with systemic symptoms such as anosmia, weight gain, and renal dysfunction." (PMID 40548244, 2025).
Anxiety (1 paper, 2022). Intense feelings of nervousness, tension, or panic often arise in response to interpersonal stresses. "The few studies available so far report on anxiety, reduced social dominance, and associative learning defects in Bbs2 and 4 knockout mice, in part due to impaired neurogenesis." (PMID 36498834, 2022).
aortic stenosis (1 paper, 2017). Aortic valve stenosis is a aortic valve disease caused by the incomplete opening of the aortic valve. "In the two patients with potential triallelism, the clinical picture of the patient with biallelic mutations in BBS2 and one putative pathogenic missense change in BBS1 was particularly serious; in fact, this patient was born with a severe congenital aortic stenosis." (PMID 28143435, 2017).
Bardet‐Biedl syndrome type 2 (1 paper, 2023). "This analysis identified the C‐terminal segment of BBS2 protein, a component of the BBSome complex, mutated in the Bardet‐Biedl syndrome type 2." (PMID 36744302, 2023).
breast carcinoma (1 paper, 2014). "Among the 69 ciliary-associated genes analyzed, seven genes showed a statistically significant decrease in expression in breast cancers (log fold change: DYNC2H1 = -0.66; IFT46 = -1.07; PKD2 = -1.67; NPHP3 = -1.10; BBS2 = -1.51; BBS4 = -0.78; TTC8 = -1.46)." (PMID 24987519, 2014).
retinal ciliopathies (1 paper, 2023). "The phenotype of the cep290 and bbs2 zebrafish models of retinal ciliopathies is characterized by the degeneration of photoreceptors, chronic inflammation, and increased proliferation of rod precursor cells." (PMID 37293546, 2023).
visual disorders (1 paper, 2016). "Eight positively selected genes within the tarsier lineage were implicated in several diseases associated with eye development and visual disorders (BBS2, BFSP2, IDUA, IL1A, IMPG1, RGR, SRD5A3 and TMC8)." (PMID 27708261, 2016).
kidney disease (4 papers, 2022 to 2025). "Kidney disease has been described as more prevalent in BBS2-, BBS7-, and BBS9-related BBS, as well as in BBS6-, BBS10-, and BBS12-related BBS." (PMID 40087798, 2025).
cancer (2 papers, 2023 to 2025). A tumor composed of atypical neoplastic, often pleomorphic cells that invade other tissues. "These modules contained several cancer regulators such as Intraflagellar Transport (IFT) complex proteins (IFT74, IFT88), BBSome complex proteins (BBS2, BBS7, BBS9, BBS12), exocyst complex components (EXOC3, EXOC4, EXOC6B, EXOC7, and EXOC8), TTC8, TTC21B, EVC, and NEK1." (PMID 40700427, 2025). "BBS2 and BBS18 have not so far been implicated in any studies relative to cancer, so the relevance of our findings cannot be compared with the published literature." (PMID 37542187, 2023).
infection (2 papers, 2021 to 2025). The state of being infected such as from the introduction of a foreign agent such as serum, vaccine, antigenic substance or organism. "In mice, IFT and BBS2 deletion mutants exhibited a very similar loss of pathogenicity both in the pooled bar-seq screen and in the individual infection experiments." (PMID 40602995, 2025). "This severe phenotype was seen in experiments where the BBS2 mutant was present alone as well as in the pooled infections, indicating that the presence of BBS2 wild-type cells did not protect the BBS2 knockout cells." (PMID 40602995, 2025).
cardiovascular disease (1 paper, 2022). "Generally, BBS10 and BBS2 patients have been reported as having more severe features than BBS1 with lower risk of cardiovascular disease." (PMID 35886001, 2022).
BBS2 also shares sentences with these, for which no sentence is quoted: diabetes (5 papers); Retinal dystrophy (5); Joubert syndrome (4); Cognitive impairment (3); genetic disorder (3); Hypertension (3); Meckel-Gruber syndrome (3); nephronophthisis (3); orofaciodigital syndrome (3); Usher syndrome (3); Alström syndrome (2); dyslipidemia (2); hypogonadism (2); LEPR deficiency (2); metabolic disease (2); myopia (2); renal dysplasia (2); Alagille syndrome (1); bipolar disorder (1); blinding (1); Brain atrophy (1); brain disorder (1); central obesity (1); choroidal sclerosis (1); choroideremia (1); cranioectodermal dysplasia (1); cyst (1); cystic kidney disease (1); deafness (1); developmental delay (1).
A further 35 diseases each share a sentence with BBS2 in 1 paper.